COL5A1 (collagen type V alpha 1 chain)
Diseases named in the same sentence as COL5A1 in open-access papers (continued):
Sharing a sentence is not in itself a finding about the gene and the disease.
tumor (continued). "The SVM_Score emerges as a robust prognostic tool reflecting tumor mechanical characteristics, while Sorafenib intervention targeting COL5A1 secretion presents a promising therapeutic strategy to mitigate LUAD aggressiveness." (PMID 38987529, 2024). "In this study, we noticed that the promoter regions of five HGs, such as KRT19, MMP1, COL11A1, SDC1, FN1, and COL5A1 were highly methylated in normal compared to tumor patients." (PMID 38639039, 2024). "Our research revealed the pivotal role of COL5A1 in influencing the mechanical properties of the tumor microenvironment." (PMID 38987529, 2024). "It promotes M2 macrophage polarization to drive the TGFβ/Smad3/COL5A1 signaling pathway, leading to tumor drug resistance." (PMID 38918587, 2024). "Silencing COL5A1 effectively inhibited tumor cell growth, invasion, and migration while enhancing apoptosis, providing experimental evidence for its potential role in LUAD treatment." (PMID 39850883, 2024). "High COL5A1 expression from myofibroblasts promoted tumor invasiveness and EMT pathway activation in LUAD cells." (PMID 38987529, 2024). "Collagen type V alpha 1 chain (COL5A1) is engaged in extracellular matrix collagen synthesis, and its aberrant deposition is considered as an important marker for tumor progression and metastasis." (PMID 39063036, 2024). "By driving the expression of onco-immune modulatory genes, such as ENO1, MUC1, COL5A1, and IL11, FABP7 enhances tumor-associated immune suppression, particularly by facilitating the infiltration of immunosuppressive cell populations within TIME." (PMID 39596296, 2024). "On the other hand, from methylation analysis, we observed that the promoter region of HGs such as KRT19, MMP1, COL11A1, SDC1, FN1, and COL5A1 is significantly methylated in normal tissue than in tumor tissue." (PMID 38639039, 2024). "When co-cultured with tumor cells, it was observed that tumor cells located near CAFs with reduced COL5A1 expression also exhibited decreased Vimentin expression." (PMID 38987529, 2024). "Integrating innovative prognostic tools, mechanistic insights into tumor-stroma interactions, and identifying Sorafenib as a modulator of COL5A1 expression collectively contribute to the evolving landscape of precision oncology." (PMID 38987529, 2024). "Results from the CCK8 assay indicated that knockdown of COL5A1 significantly inhibited the proliferation of tumor cells (p < 0.01)." (PMID 39712023, 2024). "Previous studies have also found that COL5A1 is a marker of EMT in tumor cells and can directly promote EMT." (PMID 38136265, 2023). "Our study also revealed that COL5A1 expression was related to tumor stage in most cancers and was particularly different between stages I and IV, stages II and IV, and stages I and III." (PMID 35082969, 2022). "COL5A1 also has a critical role in tumor development and was reported to promote the proliferation and metastasis of BRCA and LUAD." (PMID 35082969, 2022). "In several normal/tumor pairs (n = 5), the expression of COL5A1 in the tumor tissues was higher than that in the normal adjacent tissues." (PMID 34702798, 2021). "In the tumor stroma, the IHC expression of COL5A1, COMP, and IBSP was significantly higher in the group with BM than that in the group without BM (p = 0.001 for COL5A1, p = 0.015 for COMP, and p = 0.003 for IBSP)." (PMID 34503278, 2021). "Collagen, type V, alpha 1 (COL5A1), one of the collagen family, can promote tumor growth as an oncogenic protein in cancers." (PMID 34603443, 2021). "In contrast, we also observed that the downregulation of COL5A1 expression in tumor cells led to a functional phenotype reversal." (PMID 34702798, 2021). "In vivo and in vitro experiments found miR-582-5p inhibit tumor growth via suppressing COL5A1 expression." (PMID 33937021, 2021). "Further, we found increased expression of the fibrillar collagen proteins COL3A1 and COL5A1 in muscle-invasive tumor samples and metastatic T24 cells." (PMID 23383328, 2013).
tumor (continued). "As a result, the distribution of CAF-like astrocytes—marked by SERPINH1 and COL5A1—could help more precisely define tumor boundaries during diagnosis and treatment." (PMID 40530702, 2025). "Finally, FAP was associated with ECM and adhesion genes (FN1, COL5A1, SPOCK1, CDH13) and regulators of migration (NREP, SEMA5A), consolidating its central role in matrix deposition and tumor invasion, as previously shown." (PMID 41198614, 2025). "However, the precise role of COL5A1 in cancer remains poorly understood, and further studies are needed to clarify its function in tumor biology." (PMID 40530702, 2025). "In both the TCGA-LUAD cohort and the TMU patients, COL5A1 is highly expressed in tumor tissues." (PMID 38987529, 2024). "Additionally, treatment with Sorafenib, which targets COL5A1 secretion, attenuated the tumor-promoting effects of myofibroblast-derived COL5A1, inhibiting LUAD cell proliferation, migration, and enhancing chemosensitivity." (PMID 38987529, 2024). "In addition, we also identified several key genes involved in tumor aggressiveness, including COL5A1, VEGFA, TNC, and FN1." (PMID 38390494, 2024). "The other molecules, including IFN-γ, CXCL, CTLA-4, MTAP, SFR4/CPXM1/COL5A1, TILs, CAFs, exosomes, and peripheral blood indicators, may have suggestive significance for tumor immune microenvironment and prognosis of immunotherapy." (PMID 36860322, 2023). "By consulting the literature, we found that COL5A1 is related to immune infiltration in the tumor microenvironment (TME) of GC patients, so we wondered whether FSTL1 was also involved." (PMID 35805015, 2022). "Firstly, Oncomine was used to assess the COL5A1 expression in normal and tumor tissues." (PMID 35082969, 2022). "MiR-137-3p played a tumor-suppressive role in GC, and its target gene COL5A1 could reversely sponge miR-137-3p to relieve its targeted inhibition of FSTL1, which might promote the progression of GC by affecting immune infiltration." (PMID 35805015, 2022). "Additionally, the COL1A1 and COL5A1 were highly expressed in PTC tumor samples than in contrast to neighboring healthy samples." (PMID 35530352, 2022). "Therefore, it is necessary to preliminarily reveal the value of COL5A1 in predicting drug sensitivity and immunotherapy sensitivity of tumor cells through biological methods." (PMID 35082969, 2022). "In vivo, the decreased tumor size and weight by miR-582-5p were reversed by COL5A1 overexpression." (PMID 33937021, 2021). "COL5A1, considered as a structurally minor player playing important roles in the collagen hierarchy, was reported to promote progression and chemoresistance and affect tumor-infiltrating immune cells in multiple cancers." (PMID 34868960, 2021). "We found that the expression levels of COL5A1 increased along with tumor grades significantly." (PMID 34868960, 2021). "In summary, miR-582-5p, which was regulated by RUNX1, inhibited tumor growth and invasion by targeting COL5A1, indicating that miR-582-5p may act as a biomarker and that the RUNX1/miR-582-5p/COL5A1 axis could be a potential therapeutic target for ccRCC." (PMID 33937021, 2021). "Expression intensities of SPARC, COL1A1, COL5A1, COMP, IBSP, and THBS4 were interpreted in tumor stroma, as they were associated with ECM-related pathways, and the expression intensity of SORD was interpreted in tumor cells, as it was associated with the EMT pathway." (PMID 34503278, 2021). "Moreover, a previous study found that the overexpression of COL5A1 was correlated with tumor-infiltrating immune cells (TIICs) and enhanced the paclitaxel resistance in ovarian cancer." (PMID 34868960, 2021). "COL5A1 could be a potential therapeutic target, maybe we can change the prognosis of patients by affecting the tumor microenvironment which has important guiding significance for clinical work." (PMID 33281878, 2020). "Furthermore, localizing CAF-like astrocytes via SERPINH1/COL5A1 expression may help better delineate tumor extent during GBM diagnosis and treatment." (PMID 40530702, 2025).
tumor (continued). "Additionally, COL5A1 expression correlated with several tumor-infiltrating cells in OV." (PMID 35082969, 2022). "In our study, the data from qRT-PCR, WB, and dual luciferase reporter assay solidly confirmed that miR-29b-3p directly targeted COL1A1 and COL5A1 3′‐UTR and thus caused degradation of type I and V collagens, which could explain the downregulation of miR-29b-3p in clinical tumor tissues." (PMID 35530352, 2022). "Notably, COL5A1 was the most significantly upregulated in the tumor tissues." (PMID 33937021, 2021). "All PDGCAs expressed markers of tumor epithelial and stem cells (EPCAM, CDH1, KRT18, CA9, CD24, CD133), stromal and extracellular matrix components (COL3A1, COL5A1, DCN, PDGFRA, and PDGFRB), and mesenchymal stem cells (CD73, CD105, CD90)." (PMID 40723172, 2025). "In vitro co-culture experiments further demonstrated that GBM cells can recruit and activate astrocytes at the tumor periphery, inducing overexpression of SERPINH1 and COL5A1." (PMID 40530702, 2025). "In contrast, eight genes (COL1A1, COL5A1, COL1A2, COL3A1, WNT2, C1QTNF3, ADAMTS2, GXYLT2) exhibited elevated expression in tumor compared to normal tissue." (PMID 39062832, 2024). "Our findings indicated that CD79A, COL5A1, ERO1A, and GJB2 were significantly overexpressed in tumor tissues compared to normal tissues, while CD101 and CPA3 showed more active expression in normal lung tissues, aligning with our prior analysis." (PMID 39850883, 2024). "Identification of collagen genes COL5A1, COL5A2, and COL3A1 as top key regulators points to a tumor microenvironment with significant fibrosis and desmoplastic change." (PMID 36637997, 2023). "Not only were many collagen genes overexpressed in tumor progression between T1 and T2 stages, but also the mRNA expression of these collagen genes, such as COL1A1, COL1A2, COL3A1, COL5A1, COL5A2, COL6A2, and COL6A3, was highly positively correlated." (PMID 36596829, 2023). "COL5A1, LOXL1, and TMEM63C expression levels were significantly higher and LYSMD3 expression levels were significantly lower in tumor tissues than in the paired normal tissues." (PMID 35152572, 2022). "Significant increase in the expression of COL5A1 and LOXL1 in tumor tissues was validated by quantitative real‐time polymerase chain reaction (p < 0.05)." (PMID 35152572, 2022). "The mechanistic investigation revealed that miR-29b-3p directly targeted COL1A1 and COL5A1, thereby suppressing ECM remodeling, which is crucial for tumor invasion and metastasis." (PMID 35530352, 2022). "COL5A1 and LOXL1 expression levels were significantly higher in 18 paired tumor tissues than in cancer‐adjacent tissues (p < 0.05), consistent with the results obtained by RNA‐seq." (PMID 35152572, 2022). "Col1a1, Col1a2, Col2a1, Col3a1, and Col5a2, which were commonly found in normal ECM of mouse, pig, and human breast tissues, were also identified in tumor ECM in addition to Col4a2, Col5a1, Col6a1, Col6a2, Col6a3, and Col7a1." (PMID 36547361, 2022). "We performed differential analysis and correlation analysis of these four genes (COL3A1, COL4A1, COL5A1, and COL15A1) and tumor immune subtypes with tumor microenvironment scores." (PMID 34691289, 2021). "qRT-PCR results showed that the mRNA expression of COL1A1, IGF1, COL5A1, CXCL12, PTEN, and SPP1 were also significantly differently expressed in normal samples and tumor samples." (PMID 32641130, 2020). "The collagen family (COL1A2, COL1A1, COL6A3, and COL5A1), DCN, FBLN1, and POSTN were the most abundant components of the tumor ECM." (PMID 33613617, 2020). "The analysis of the corresponding tumor and non-tumor samples also revealed upregulation of COMP, matrix proteins such as COL5A1, COL11A1, and FN1, and genes of the Wnt pathway (WNT7B, FZD10, SFRP2), while PLCB1, CAMK2B, PLCB4 and WIF1 are downregulated." (PMID 33227073, 2020).
tumor (continued). "GPNMB and CoL5A1 are the reported oncogenes; PMEPA1, POMT2, VGLL4 and SUMF1 show better survival and thus suggest tumor suppressive role are being regulated by EZH2 signifying its dual role." (PMID 30760814, 2019). "We propose that changes in the expression of SERPINH1 and COL5A1 may induce astrocytes to adopt CAF-like characteristics, potentially promoting tumor invasiveness and metastasis." (PMID 40530702, 2025). "Stabilizing COL5A1 mRNA and promoting EMT and tumor metastasis." (PMID 41446042, 2025). "Consistent with the results from non-tumor samples, all the TIMGs that we identified (ENO1, MUC1, COL5A1, COL11A1, IL11, AIM2, JUNB) as well as FABP7, exhibited significantly or moderately elevated expression in multiple TCGA tumors, including GBM, compared to normal tissues." (PMID 39596296, 2024). "The fact that Collagen signatures exhibit strong predictive power may be because these members themselves (COL1A1, COL4A3, COL5A1, COL11A1, COL22A1) have been reported to predict tumor prognosis." (PMID 37476379, 2023). "In parallel, the scRNA data from 15 PDAC tissues samples also showed higher infiltration of cells expressing SMC/fibroblast markers (PDPN, COL5A1, COL22A1, TIMP3, SPARC, WT1, GFPT2) in samples with higher proportions/fractions of MUC16-expressing tumor (epithelial) cells (n = 7)." (PMID 36816942, 2023). "On the other hand, COL1A2, COL3A1, COL5A1, FN1, and SPARC may be more involved in tumor progression from stage 1 to stage 2, at which the tumor cells gain the ability to invade surrounding tissues." (PMID 35739492, 2022). "Firstly, tumor cells secrete Tsp2 to induce the transformation of normal fibroblasts to TAFs, and TAFs remodel the extracellular matrix by secreting COL1A1, COL1A2, COL5A1, FN1, and VCAN." (PMID 35982904, 2022). "Further analysis showed that there was a negative correlation between miR-582-5p and COL5A1 in tumor tissues (r=0.6433, P<0.01)." (PMID 33937021, 2021). "When signatures from plasma- and ascites-derived sEVs were compared we found significant differences in expression of COL5A1, AEBP1, TIMP3, and ACTB at week 3 of tumor progression, suggesting that ascites-derived sEVs are likely a stronger indicator of tumor presence compared to plasma-derived sEVs." (PMID 34868914, 2021). "In addition, we have also identified a set of genes that are regulated in the opposite way by 7SK and FOXJ3/THRA, including four positive regulators in tumor migration (CXCL1, SYDE1, COL5A1, and HIF1A)." (PMID 33868377, 2021). "We showed that genes co-expressed with WISP1 may act as tumor promotors by regulating ECM organization, with the collagen members COL6A3, COL5A1, and COL8A1 being key genes in a majority of cancers." (PMID 32523603, 2020). "It indicated that the COL1A1, IGF1, COL5A1, CXCL12, PTEN, and SPP1 were significantly differently expressed in EC tumor compared with those in normal samples (P = 4.93E−02, P = 5.24E−03, P = 2.83E−04, P = 1.58E−06, P = 2.11E−12, and P = 6.91E−13, respectively)." (PMID 32641130, 2020). "The PanCancer pathway panel includes multiple collagen genes and our data also showed significantly higher expression of COL11A1, fold change 24.99, p = 0.001, COL5A1, fold change 3.91, p = 2.0x10-8 and COL1A1, fold change 8.40, p = 5.65x10-8 in ILC tumor relative to adjacent normal tissue." (PMID 27078887, 2016). "The spatial localization of HYP peptides for COL1A1, COL1A2, COL5A1 and COL3A1 exhibited distinct region-specific patterns in dormant D-HEp3 compared to awakened P4HA2-depleted D-HEp3 cells, suggesting differential regulation of collagen hydroxylation across tumor zones." (PMID 40671813, 2025). "We detected 24 genes across the tumor tROIs that showed a high CV (i.e., were among the genes with the top 20% highest CV in seven out of seven cases), such as multiple collagens (COL1A1, COL1A2, COL3A1, COL5A1, COL5A2), S100A8, S100A9, FN1, or Early growth response protein 1 (EGR1)." (PMID 37511126, 2023).
tumor (continued). "COL5A1 potentially influenced the tumor progression through immune-related pathways, negative regulation of immune system processes, chemokine signaling pathways, JAK-STAT pathways, T cell receptor pathways, lymphocyte migration, and antigen processing and presentation, among other processes." (PMID 35082969, 2022). "Furthermore, the expression of COL5A1 mRNA and protein also decreased in a stepwise fashion with the increasing level of miR‐145 in tumour/serum samples genotyped as AA, AG and GG, respectively, suggesting a negative correlation between COL5A1 and miR‐145." (PMID 32720739, 2020). "The relative expression of COL1A1, IGF1, COL5A1, CXCL12, and PTEN in tumor samples was significantly lower compared to those in adjacent normal samples (P < 0.05), while SPP1 expression was significantly higher in tumor samples compared to the adjacent normal samples (P < 0.05)." (PMID 32641130, 2020). "Interestingly, our results show that mutations in COL5A1 are present in NAT rather than in CRC samples, which can indicate some sort of preventive effect or may contrarily serve as a marker of tumor progression." (PMID 39859451, 2025). "The expression of COL5A1 or FSTL1 was significantly positively correlated with the three types of scores, and the correlations between the expression of FSTL1 and those scores were significantly higher than that of COL5A1, suggesting that FSTL1 may affect tumor immune infiltration in GC patients." (PMID 35805015, 2022). "According to the PCR results, we found that COL5A1 in OC cells was generally downregulated, what’s more, SKOV-3 and A2780 were not resistant cells, indicating that cisplatin resistance may be more related to the tumor microenvironment of the human body, which is worth further study." (PMID 33281878, 2020). "Although no studies of COL5A1 and MFAP5 in ESCC have been reported, these two genes are involved in tumor metastasis in other types of tumors." (PMID 38136265, 2023). "The amplification of genes such as COL5A1, IDO1, and GOLIM4 were in accordance with their higher expression in tumor samples, whereas no significant change of protein or phosphorylation levels was observed for genes with genomic amplification, such as CD4, CD7, LIME1, UNC93B1, C1S, C1R, or C8G." (PMID 34400640, 2021). "As shown by the results and in tumour/serum samples genotyped as AA, AG and GG, the expression of both MALAT1 and COL5A1 was down‐regulated in a stepwise fashion, while the expression of miR‐145 was increased, suggesting a potential negative relationship between MALAT1/COL5A1 and miR‐145." (PMID 32720739, 2020).